PF4 (platelet factor 4)
Diseases named in the same sentence as PF4 in open-access papers (continued):
Sharing a sentence is not in itself a finding about the gene and the disease.
infection (continued). "In addition to blood coagulation, PF4 has additional activities, with elevated PF4 expression found after trauma and in response to infection." (PMID 34639132, 2021). "It was already determined that Pf4r was responsible for conferring immunity to Pf4 infection." (PMID 34452479, 2021). "PF4 and polyphosphates can successively bind on lipid A on Gram-negative bacteria, leading to opsonization of bacteria by anti-PF4/polyanion antibodies, enabling better host defense against infection." (PMID 33578859, 2021). "Studying the presence of PF4 antibodies in recipients of other types of vaccines and after natural infection could help us characterize the triggering antigens (adenovirus, spike protein, or other) that induce the production of such antibodies." (PMID 34358129, 2021). "The main function of PF4 is to promote the coagulation of blood, but this cytokine also plays a role in innate and adaptive immunity when platelets are activated in response to infections." (PMID 34685765, 2021). "During infections, activated platelets release PF4 in response to microorganisms." (PMID 33050376, 2020). "Furthermore, we demonstrate that the repressor C in Pf4 and Pf5 confer immunity to Pf4 infection and Pf4 phages released from PAO1 overexpressing xisF4 were also capable of re‐infecting PAO1 wild‐type strain." (PMID 30475408, 2019). "Among these genes, several encode chemokines (IL8, CXCL1, CXCL10, CXCL11, CXCL9, PF4, PPBP), a family of small proteins that play important roles in the immune system through leukocyte recruitment, cell communication and cell activation during infection." (PMID 26791855, 2016). "It is known that sub-MIC concentrations of CIP induce Pf4 prophages and that Pf4 prophage can become superinfective and induce cell lysis, leading to liberation at the site of infection of virulence factors that might be recognized by the immune cells inducing an inflammatory response." (PMID 38478426, 2024). "PF4 has been reported to bind LPS, and this neutralizing effect may add to the action of PF4 during infections caused by Gram-negative bacteria." (PMID 37868353, 2023). "In fact, WBC uptake depends on the enhanced influx of granulocytes to the infection/inflammation site mediated via immunological binding to cellular antigens and chemotactic peptides (f-Met-Leu-Phe), cytokines (interleukin 1 (IL-1), IL-8, Platelet factor 4 PF-4), and complement factors (C5a, C5adR)." (PMID 32235478, 2020). "In parallel, platelet chemokines and antimicrobial peptides such as platelet factor 4 (CXCL4/PF4), C-X-C motif chemokine ligand 7 (CXCL7), defensins and thrombocidins, modulate innate immunity and host defense, supporting infection control during early repair." (PMID 41369338, 2025). "Activated platelets release a variety of cytokines, chemokines, and growth factors, such as platelet factor 4 (PF4) and transforming growth factor-beta (TGF-β), which recruit and activate macrophages at sites of injury or infection." (PMID 40333325, 2025). "Although platelets are not traditionally seen as classical cytokine-producers, accumulating evidence supports their capacity to store or synthesize immunomodulatory mediators PF4 and TGF-β in response to stress or infection." (PMID 41441628, 2025). "Many phages, including P. aeruginosa lytic tailed phages QDWS, D3112, phiKMV, and MPK7, as well as ssDNA filamentous phages Pf4 and RNA phage PP7, all require T4P for infection." (PMID 39772127, 2024). "The filamentous phage Pf4 that infects Pseudomonas aeruginosa strain PAO1 enhances bacterial virulence in murine lung and wound infection models." (PMID 36800381, 2023). "It has been reported that PF4 and PPBP belonged to the CXC chemokine family and played roles in platelet activation, platelet degranulation, immune response to infection, activation of neutrophils and monocytes, and tumorigenesis." (PMID 35571050, 2022).
infection (continued). "The aim of the study was to answer several clinically related questions—whether Pf4 can be induced during antibiotic or phage therapy, whether the released virions are capable to infect other P. aeruginosa strains, and how this phage influences virulence factors upon infection of new hosts." (PMID 35746731, 2022). "The ZCO1 phage showed a greater infection capacity in both M9-casein and M9-CAA media than Pf4 in the WT and ΔCRISPR strains." (PMID 35699339, 2022). "During this infection, the penetration of HIV into hepatic cells is inhibited following the interaction of the chemokine PF-4 (CXC4) as well as RANTES (CCL-5) secreted by platelets." (PMID 34970260, 2021). "Chemokine (C‐X‐C motif) ligand 4 (CXCL4), also known as PF4, is a component of the innate immune response of multiple cell types, including platelets and monocytes/macrophages, to infection by various pathogens." (PMID 34691454, 2021). "The curing process of Pf4 from PAO1 was very efficient, with a high yield of cured mutants that can serve as a surrogate for infection from PAO1-produced phages." (PMID 33670076, 2021). "During this infection, the chemokine CXC4 (PF-4) is also secreted from the EVs of platelets, which leads to inhibition of hepatic cell apoptosis and increase in the possibility of spreading HIV." (PMID 34970260, 2021). "Our study indicated that three cytokines (Fas, PF4 and IL-22) were upregulated in WSSV-infected shrimp at 6 h post-infection." (PMID 27631372, 2016). "FCPLJ treatment downregulated several inflammatory cytokine genes in the liver, including CCL6/MRP-1, CCL8/MCP-2, CCL12/MCP-5, CCL17/TARC, IL1R1, IL1RN/IL1Ra, NAMPT/PBEF1, and PF4/CXCL4, indicating its potential role in mitigating inflammation during infection." (PMID 40007026, 2025). "Unlike Ff and M13 filamentous phages infecting E. coli, the infection of Pf phages including superinfective Pf4 and Pf6 can lead to host death and form lytic phage-like plaques on bacterial lawns." (PMID 39861901, 2025). "PF4 overexpression suppressed the replication of CA6 and EVD68 as is evident in VP1 protein levels of intracellular and in the culture supernatant over time, especially after 24 h post-infection." (PMID 39772852, 2025). "The findings we present in this work indicate that the presence of Pf4 phage and OMVs could be associated with negative outcomes in patients infected with P. aeruginosa, through ineffective macrophage activation and subsequent impaired recruitment of neutrophils at early stages of infection." (PMID 37965262, 2023). "Following infection of the LESB58 strain with Pf4 phage, there was no significant change in PfLES58 phage expression." (PMID 35746731, 2022). "The differences in properties of Pf4-infected, and uninfected PA14 and LESB58 strains were obvious, as infection with Pf4 significantly decreased cell autoaggregation, pyoverdine, and pyocyanin production, while significantly increased swimming motility and biofilm production in both strains." (PMID 35746731, 2022). "After 24 h incubation, the difference in growth cannot be observed, so the Pf4 infection has no long-term influence on PA14 and LESB58 growth." (PMID 35746731, 2022). "The successful infection of the strains by Pf4 is not surprising, as it has been previously documented that one bacterial strain can carry several different or even the same prophages from the family Inoviridae." (PMID 35746731, 2022). "The mutation in the dimerisation site also affected Pf4r’s function as an immunity protein as the 788799A>G (Ser4Pro) removed the host immunity to Pf4 infection while the 788570C>A (Arg80Leu) does not." (PMID 34452479, 2021). "Pf4 also contributes to the virulence of PAO1, as shown by the increased survival of the strain without Pf4 using a mice infection model." (PMID 30475408, 2019). "The results indicated that PF4 took effects on the WSSV infection at 12–24 but not 48–72 h post-infection." (PMID 27631372, 2016).
infection (continued). "To determine whether PF4 has a role in driving KLF4 expression during ECM we isolated spleens from infected WT and PF4−/− mice on day 4 post-infection and quantified KLF4 expression by qRT-PCR." (PMID 20454664, 2010). "In addition, the lysogenized Pf4 prophage is believed to confer P. aeruginosa PAO1 resistance to infections by Pf4 phages because only the Pf4-deletion mutant but not the wild type can be lysed by Pf4." (PMID 38365255, 2024). "However, it seems the opposite happened with PA14 and LESB58 P. aeruginosa cells upon infection with Pf4 phage, as autoaggregation was decreased—non-lysogenic strains were moderately aggregative, but after infection with Pf4 phage, they became non-aggregative." (PMID 35746731, 2022). "Furthermore, Pf4 superinfection and expression of PfsE were able to prevent infection by phage OMKO, a lytic pili-dependent phage, but not LPS-5, another pili-independent phage species." (PMID 35038902, 2022). "The reduced fitness of the ΔCRISPR strains at <90% of the initial population in M9-casein may be due to their response to Pf4 infection rather than QS regulation." (PMID 35699339, 2022). "Notably, at a later stage (day 7 post infection) when IAV was hardly detected in the immune cells, a group of platelet factor 4-positive (Pf4+)-macrophages generated another wave of pro-inflammatory factors, which were probably the precursors of alveolar macrophages (AMs)." (PMID 32101596, 2020). "In addition, coculture with platelets is able to prevent T cell infection through PF4-dependent mechanisms regardless of CCR5 or CXCR4 coreceptor tropism." (PMID 29761104, 2018). "At 40 h after infection, platelet CD63 expression was reduced relative to pre-infection, yet not different between Stk11fl/fl × Pf4-Cre and control mice." (PMID 40332331, 2025).
cancer (77 papers, 2008 to 2025). A tumor composed of atypical neoplastic, often pleomorphic cells that invade other tissues. "Consistently, the levels of angiogenic factors, such as VEGF, IL-6, TSP-1, PF4, TGFβ, and PDGFβ were linked not only with the platelet count but also with cancer stage and patient prognosis." (PMID 36362186, 2022). "The TGFB1 pathway is pro-metastatic in late stages of cancer and, like PF4, TGFB1 has been linked to platelet activity in cancer patients." (PMID 31215484, 2019). "The majority of the genes identified here, including but not limited to CCR1, CCR2, CCR3, ENA78, GPCR, GRO1, GRO2/GRO3, IP10, IL-8, NAP-2, PF-4 have been recently shown to associate with the progression of various types of cancer." (PMID 22347499, 2012). "Besides the reported NSCLC candidate markers, we found sizeable noteworthy proteins closely related to other cancers, such as alpha-1B-glycoprotein, Complement C1q subcomponent subunit A, fibrinogen alpha/gamma chain, fibulin-1, platelet factor 4 and its variant." (PMID 23284758, 2012). "Genes often found to be epigenetically silenced or with low expression levels in ovarian or other cancers (Adora1, Bmp3, Ccl6, Ephx2, Lefty2, Pf4, Socs2) were downregulated by MOSE-LTICv in the OFB." (PMID 38264656, 2023). "Overall, PF-4 has been identified as a cancer-enhancing molecule that alters bone marrow hematopoiesis and increases platelet accumulation in the TME." (PMID 37693009, 2023). "They found an increased expression of PF4 in cancer patients compared to platelet samples from healthy donors." (PMID 37176055, 2023). "Overexpression of PF-4 has been observed in cancers such as lung cancer and correlates with decreased patient survival." (PMID 37693009, 2023). "mCHT inhibits the expression of pro-angiogenic factors, such as VEGF, VEGFR2, bFGF, and SDF1, and induces the production of angiogenesis inhibitors, such as thrombospondin-1, in both stromal and cancer cells, platelet factor-4, and endostatin." (PMID 36012949, 2022). "Platelet markers that alter significantly in the presence of cancer have been identified as beta-2-microglobulin (B2M), pro-platelet basic protein (PPBP), thymosin beta 4 X-Linked (TMSB4X), and platelet factor 4 (PF4)." (PMID 35096878, 2021). "Detection of platelet-derived growth factor, platelet factor 4 (PF-4) and platelet-derived endothelial cell growth factor was suggested for diagnosis of several cancers." (PMID 29344361, 2018). "For the clinical relevance of our studies, we investigated the possible correlation of PF4 expression levels with human cancer progression using publically available datasets and Genespring GX 10.0 software." (PMID 27223426, 2017). "Deletion of PF4 increased cancer metastasis, which was mediated through two distinct mechanisms: compromised blood vessel integrity, and increased production of HSCs as well as Gr-1+CD11b+ cells." (PMID 27223426, 2017). "In PECT plasma, we found two-fold higher PF4 values in cancer patients compared to healthy controls." (PMID 21637343, 2011). "In our study, in both healthy controls and cancer patients PF4 concentrations were 50–100 times higher in standard citrate plasma (collected with tourniquet) than in PECT plasma (collected without tourniquet)." (PMID 21637343, 2011). "Furthermore, PF4 has a high affinity to polyanions on many cell surfaces such as monocytes, neutrophils, endothelial, and even cancer cells." (PMID 38540666, 2024). "In addition, a subset of these genes has been associated with cancer therapy responses (AZU1, CDCA3, CEACAM6, EN1, PF4)." (PMID 35008420, 2022). "In previous studies, researchers have determined that PF4 can be used as an antiangiogenic factor to inhibit endothelial cell proliferation, migration, and angiogenesis in a variety of in vitro and in vivo models of cancer." (PMID 35498539, 2022).
cancer (continued). "However, in the presence of platelets, PF4 promoted cell proliferation on day 6, indicating that PF4 can promote cancer metastasis if cells enter the blood circulation." (PMID 34440575, 2021). "Determining the exact source of increased PF4 levels in patient with cancer is complicated." (PMID 31215484, 2019). "The negative correlation of PF4 expression levels with human cancer progression strongly supports the therapeutic potential of PF4 and its non-allelic variant CXCL4L1." (PMID 27223426, 2017). "Regulating platelet secretion could be a viable target for anti-metastatic therapies, and indeed, PF-4 is being developed as a novel anti-angiogenic cancer therapy." (PMID 25468720, 2015). "Thus recombinant PF4 has been proposed as one alternative option for cancer therapy." (PMID 27223426, 2017). "While much of the biology of platelet-associated PF-4 and CTAP-III is likely to be harnessed with therapeutic intent only in the future, an obvious immediate clinical application may be to use them as biomarkers of cancer presence and/or therapeutic response." (PMID 23800319, 2013). "However, an increased PF4 concentration in individual platelets of cancer patients may also have contributed to the increased PF4 concentration in PECT plasma." (PMID 21637343, 2011). "Another study found elevated levels of VEGF, PF4, and PDGF in platelets of colorectal cancer patients, demonstrating their utility in distinguishing healthy individuals from those with cancer." (PMID 39934930, 2025). "Beyond nucleic acids, the level of platelet-derived releases such as GITRL, GARP, PF4, and VEGF alter parallel to cancer progression, offering additional monitoring tools." (PMID 40514754, 2025). "To the best of our knowledge, we firstly described considerable elevation of IL-6, IL-8, TNF-α, IP-10, HCC-1, and PF-4 levels in OSCC compared to OL patients, being detectable from early cancer stages." (PMID 33924500, 2021). "Three cancer biomarkers including prostate specific antigen (PSA), prostate specific membrane antigen (PSMA) and platelet factor-4 (PF-4) were tested and the LOD was determined to be 300–500 fg/mL in undiluted calf serum." (PMID 29258216, 2017). "On the other hand, platelets also contain anti-angiogenic factors (such as PF-4, TSP-1 and endostatin) that can limit cancer survival and growth." (PMID 25468720, 2015). "Compared with controls group, the median levels of VEGF, PF4, and PDGF-BB were significantly increased in PP from cancer patients." (PMID 25379550, 2014). "Finally, TEPs are an emerging concept where cancer cells activate platelets which, in turn, promote cancer progression through upregulation of certain factors, including VEGF, PDGF, and PF4 that remain elevated in CRC patients." (PMID 36077774, 2022). "For example, concentrations of vascular endothelial growth factor (VEGF), platelet-derived growth factor (PDGF), platelet factor 4 (PF4), connective tissue-activating peptide III (CTAPIII) and thrombospondin-1 (TSP-1) in platelets were altered depending on the types of cancer." (PMID 34722319, 2021). "Platelet factor 4 (PF-4) or CXCL14, also known as BRAK is a highly conserved homeostatic chemokine, responsible for immune cell recruitment, maturation, and its influence on epithelial cell motility is thought to be a key modulatory factor in cancer." (PMID 33924500, 2021). "Although it is one of the most studied intracellular signaling pathway in cancer 16, its molecular relationship with Pf4 has not been established." (PMID 34421345, 2021). "Several human studies performed in cancer patients revealed elevated levels of circulating angiogenesis-regulator proteins versus healthy subjects, such as VEGF, ANGPT-1, MMP-2, platelet factor 4 (PF-4), and PDGF, which can be uptaken by platelets." (PMID 33339204, 2020).
cancer (continued). "The level of PDGF (AUC: 0.856, 95% CI: 0.771–0.940), PF4 (AUC: 0.735, 95% CI: 0.612–0.859), VEGF (AUC: 0.789, 95% CI: 0.694–0.884), and TGF-β1 (AUC: 0.763, 95% CI: 0.658–0.868) in PP is significantly different between the cancer groups and control groups." (PMID 25379550, 2014). "The researchers compared sP-selectin, sCD40L, PF4, and TSP-1 among three groups: cancer patients with VTE, cancer patients without VTE, and healthy subjects." (PMID 34235190, 2021). "Our current data indicated that VEGF, PF4, PDGF-BB, and TGF-β1 levels were elevated in PP of the cancer group but not in PPP." (PMID 25379550, 2014).